TNF (tumor necrosis factor)
Diseases named in the same sentence as TNF in open-access papers (continued):
Sharing a sentence is not in itself a finding about the gene and the disease.
atherosclerosis (continued). "NF-κB activation leads to the production of pro-inflammatory cytokines such as IL-6, TNF-α, and IL-1β, which drive atherosclerosis, myocardial fibrosis, and immune evasion in tumors." (PMID 40227756, 2025). "A study involving 37 individuals at heightened risk for atherosclerosis, who were undergoing standard CVD treatment, demonstrated that G. lucidum PsP significantly reduced levels of hs‐CRP, IL‐6, TNF‐α, and MDA." (PMID 40510787, 2025). "During the progression of atherosclerosis, TNF-α mediates its inflammatory response and physiological functions by binding to its receptors, TNFR1 in its secreted form and TNFR2 in its membrane form." (PMID 40243563, 2025). "KEGG pathway analysis demonstrated significant enrichment in: Pertussis, Lipid and atherosclerosis, NF-kappa B signaling pathway, Toll-like receptor signaling pathway, TNF signaling pathway." (PMID 41479901, 2025). "Inflammation drives atherosclerosis growth, with cytokines like interleukin-1, interleukin-6, and tumor necrosis factor sparking the acute-phase reaction and curbing albumin synthesis." (PMID 41536368, 2025). "The crucial role of RSV in atherosclerosis is also due to its anti-inflammatory properties; in fact, it acts by preventing the damage to elastin fibers induced by TNF-α—induced in aortic tissue." (PMID 41228388, 2025). "This study suggests a link between elevated levels of IL-17A and TNF-α and subclinical atherosclerosis." (PMID 39104857, 2024). "In the pathological processes of both gout and atherosclerosis, cytokines, such as tumor necrosis factor alpha (TNF-α) as well as interleukins (ILs), play central roles in inflammation and immune regulation." (PMID 39677038, 2024). "Some KEGG pathways related to cell cycle regulation and growth (e.g., ‘Lipid and atherosclerosis’, ‘Vascular smooth muscle contraction’, ‘TNF signalling pathway’) were over represented, too." (PMID 38834875, 2024). "KEGG analysis of these genes highlighted several inflammation-related pathways, including cytokine-cytokine receptor interaction, TNF signaling pathway, NF-κB signaling pathway, fluid shear stress and atherosclerosis, and chemokine signaling." (PMID 38741032, 2024). "This response alleviates inflammation by reducing pro-inflammatory markers such as TNF-α and IL-6, which play a role in the progression of atherosclerosis." (PMID 39728298, 2024). "For example, macrophages secrete vimentin during atherosclerosis, which stimulates pro-inflammatory cytokines such as interleukin-6 (IL-6) and tumor necrosis factor-α (TNF-α)." (PMID 39057066, 2024). "The review found that TNF-α inhibitors significantly improved atherosclerosis markers such as CIMT, aPWV, FAI, and C-reactive protein (CRP), with reductions in these markers compared to no treatment, phototherapy, and IL-12/23 inhibitors." (PMID 39739136, 2024). "According to the value of adjust P and target count, the most critical paths include the GE − RAGE signaling pathway in diabetic complications, the TNF signaling pathway, and pathways involved in fluid shear stress and atherosclerosis." (PMID 38728503, 2024). "TNF-α plays a significant role in promoting atherosclerosis, inducing the expression of cellular adhesion molecules, and facilitating the adhesion of leukocytes to the vascular endothelium." (PMID 38672697, 2024). "The JAK-STAT pathway also plays a crucial role in atherosclerosis through its action on IL-6 and TNF." (PMID 38929699, 2024). "Previous studies demonstrate that TNF-α plays a fundamental role in endothelial inflammation and initiation of atherosclerosis." (PMID 38397822, 2024). "KEGG enrichment analysis suggested that OS‐DEGs tended to be highly involved in the lipid and atherosclerosis, TNF, ROS, and IL‐17 pathways." (PMID 39172048, 2024). "According to our results, chemokine signaling pathway, regulation of actin cytoskeleton, and TNF signaling pathway seemed to be activated in gout complicated with atherosclerosis." (PMID 38368442, 2024).
atherosclerosis (continued). "KEGG enrichment analysis showed that these shared targets were strongly linked to the PI3K-Akt signaling pathway, fluid shear stress/lipid and atherosclerosis, and the TNF signaling pathway." (PMID 38365767, 2024). "For instance, salivary cytokines such as IL-6 and TNF-α were suggested as potential markers for atherosclerosis due to their significant increase in atherosclerosis patients." (PMID 38304464, 2024). "KEGG analysis identified 182 enriched pathways (P < 0.05), with prominent pathways including AGE–RAGE signaling, lipid and atherosclerosis, Chagas disease, tumor necrosis factor (TNF), IL-17, and HIF-1 signaling pathways." (PMID 39493720, 2024). "LDGs secrete proinflammatory cytokines involved in disease pathogenesis and in atherosclerosis: TNF-α, IFN-γ and type I IFN." (PMID 38929699, 2024). "M1 macrophages primarily drive inflammatory responses and disease progression in atherosclerosis through the secretion of pro-inflammatory cytokines (such as IL-1β, IL-6, and TNF-α) and the generation of reactive oxygen species (ROS)." (PMID 39726810, 2024). "The KEGG enrichment analysis identified potential targets in several pathways, including alcoholic liver disease, lipid and atherosclerosis-related pathways, insulin resistance, TNF signaling pathway, etc." (PMID 39372201, 2024). "In response to MP/NP exposure, the body can release pro-inflammatory cytokines, such as interleukin-6 (IL-6) and tumor necrosis factor-alpha (TNF-α), which play key roles in vascular inflammation and atherosclerosis development." (PMID 39453150, 2024). "Cell activation, proliferation, and secretion of proinflammatory cytokines like IFN-γ, TNF-α, IL-2, IL-3, and lymphotoxin (LT) can promote atherosclerosis by maintaining chronic inflammation and inducing foam cell formation ​." (PMID 39463572, 2024). "Previous studies demonstrate that endothelial inflammation induced by TNF-α plays a fundamental role in the initiation and progression of atherosclerosis." (PMID 38397822, 2024). "These shared results included pathways such as the TNF signaling pathway, IL-17 signaling pathway, lipid metabolism, and atherosclerosis." (PMID 38830963, 2024). "Other notable pathways included lipid metabolism and atherogenesis, fluid shear stress and its role in atherosclerosis, and TNF signaling." (PMID 39493720, 2024). "These pathways can promote the release of inflammatory cytokines, such as tumor necrosis factor-alpha (TNF-α) and interleukin-6 (IL-6), which have been shown to contribute to endothelial dysfunction and atherosclerosis." (PMID 39057624, 2024). "Some adipokines, including TNF-α, IL-6, visfatin, and leptin, are recognized as pro-inflammatory cytokines that promote the progression of atherosclerosis and contribute to the development of acute coronary syndromes (ACSs)." (PMID 39335646, 2024). "Pro-inflammatory cytokines such as TNF-α and IL-1β are well-known pro-atherogenic, and inhibiting these cytokines attenuates atherosclerosis." (PMID 39769009, 2024). "According to KEGG analysis, DEGs were significantly enriched in IL-17 signaling pathway, TNF signaling pathway, fluid shear stress, and atherosclerosis." (PMID 39519172, 2024). "Plaque macrophages increase the expression of proinflammatory cytokines such as IL-6, IL-1β, and TNF-α, which are the first-wave inflammatory cytokines that impact atherosclerosis substantially." (PMID 36536168, 2024). "TNF‐α can cause pathological damage, damage vascular endothelial cells, aggravate foot disease, and TNF‐α has a certain correlation with atherosclerosis." (PMID 38577990, 2024). "TNF-α has been reported to exacerbate both atherosclerosis and restenosis, and several studies have identified the pro-inflammatory role of TNF-α in these cardiovascular disease conditions." (PMID 38611112, 2024). "There is one randomized clinical trial explores the differential impacts of TNF-α inhibitors and fumaric acid on atherosclerosis." (PMID 39739136, 2024).
atherosclerosis (continued). "KEGG were mainly concentrated in fluid shear stress and atherosclerosis, IL-17 and TNF signaling pathways, and validation of top 20 genes with significant fold change value were consistent with RNA-seq." (PMID 38594623, 2024). "The main pathways identified were the TNF signaling pathway, NF-κB signaling pathway, and lipid metabolism related to atherosclerosis." (PMID 38962312, 2024). "For flaxseed oil exhibited anti-atherosclerosis activity in high-fat diet-induced ApoE−/− mice, the acetic acid and propionic acid were negatively correlated with LPS, TNF-α, IL-1β, and IL-17A in plasma and with TNF-α, IL-1β, and IL-6 in the aorta." (PMID 39403395, 2024). "TNF-α contributes to endothelial cell dysfunction in several key ways, which are pivotal in the early stages of atherosclerosis." (PMID 39080547, 2024). "APG can improve atherosclerosis by stimulating apoptosis of macrophages and downregulating the secretion of cytokines (TNF-α, IL-1β, and IL-6)." (PMID 39830346, 2024). "There are two pilot and prospective cohort studies that assessed the comparative effectiveness of TNF-α inhibitors and phototherapy on atherosclerosis." (PMID 39739136, 2024). "Alisol A can bind to and inhibit TNF, thereby exerting cytoprotective effect and alleviating atherosclerosis." (PMID 39525632, 2024). "TNF is a key driver of inflammation in atherosclerosis, targeting the expression of numerous inflammatory genes in different cells of the vessel wall, including the endothelial cells." (PMID 39201392, 2024). "MIAT activation was also demonstrated to enhance angiogenesis and increase the expression of inflammatory factors (IL-1β, IL-6, and TNF-α) in mice with atherosclerosis." (PMID 39273193, 2024). "Conversely, Module 2 showcased connections with IL-17, TNF, and chemokine signaling pathways, alongside pathways related to lipid metabolism and atherosclerosis." (PMID 39346909, 2024). "Activation of P90RSK in macrophages guides the expression of pro-inflammatory genes like TNF-α, which in turn facilitates atherosclerosis." (PMID 38606153, 2024). "The KEGG pathway analysis revealed a primary enrichment of these key SONFH genes in pathways including Chemokine signalling, Toll-like receptor signalling, Lipid and atherosclerosis, NF-kappa B signalling, TNF signalling, and IL-17 signalling." (PMID 39069636, 2024). "According to our results, typical levels of SASP (TNF-α, and IL-6) in serum from atherosclerosis mice were higher, while paeonol significantly decreased TNF-α and IL-6 compared with the model group." (PMID 38202844, 2024). "It is known that TNF promotes atherosclerosis by increasing LDL transcytosis across endothelial cells, thereby facilitating LDL retention in vascular walls through NF-κB and PPAR-γ activation." (PMID 38396488, 2024). "Existing research has demonstrated the pivotal roles of NLRP3 inflammasome, IL-1β, and TNF in atherosclerosis." (PMID 38322269, 2024). "Previous sections of this paper have highlighted how inflammatory cytokines such as TNF-α, IL-6, and IL-1β contribute to both the RA disease process and atherosclerosis." (PMID 39062180, 2024). "TNF-α drives endothelial dysfunction, one of the earliest stages of plaque formation in atherosclerosis." (PMID 39062180, 2024). "The expression levels of miR-146a correlate with the expression levels of IL-6 and TNFα in patients with atherosclerosis." (PMID 38927529, 2024). "Enrichment analysis showed that the AGE-RAGE in diabetic complications, fluid shear stress and atherosclerosis, and TNF signaling pathway were potentially involved in the action of ginseng against AIC." (PMID 39243097, 2024). "Kyoto Encyclopedia of Genes and Genomes (KEGG) analysis showed that the DEG-ERs were mainly involved in lipid and atherosclerosis, tumor necrosis factor signaling pathway, and cellular senescence." (PMID 38549776, 2024).
atherosclerosis (continued). "Pro-inflammatory cytokines, such as IL-6 and TNF-α, are elevated in both conditions and inflammation plays a significant role in the development of atherosclerosis, promoting endothelial dysfunction and plaque formation in cardiovascular disorders." (PMID 38441007, 2024). "Through LASSO analysis, we ultimately identified CCL3, TNF, CCR2, and CCR5 as key genes, which showed high diagnostic value in gout and atherosclerosis through ROC curve analysis." (PMID 39677038, 2024). "Elevated HOTTIP has been demonstrated in atherosclerosis and its levels are induced by pro-inflammatory TNF-α." (PMID 38238652, 2024). "The Top 10 KEGG pathways indicated that safflower mainly acts against PAH via the TNF signaling pathway, Th17 cell differentiation, and prostate cancer, as well as lipid and atherosclerosis pathways." (PMID 39155275, 2024). "Mature DCs can exacerbate endothelial inflammation and atherosclerosis by activating the TNF‐α‐mediated NF‐κB pathway." (PMID 38334236, 2024). "Tumor necrosis factor α (TNF‐α), another important cytokine in atherosclerosis, plays an important and key role in the occurrence and development of atherosclerotic plaques." (PMID 39669190, 2024). "There are four observational studies that examine the atherosclerosis progression in patients treated with TNF-α inhibitors versus methotrexate." (PMID 39739136, 2024). "TNF, a critical inflammatory factor, was proven to possess significant functions in the biological mechanisms of both gout and atherosclerosis." (PMID 39677038, 2024). "The KEGG analysis revealed that the most enriched pathway was ferroptosis (5 genes), followed by the TNF signaling pathway (7 genes) and fluid shear stress and atherosclerosis (7 genes)." (PMID 38830963, 2024). "Potential targets such as GAPDH, AKT1, TNF, IL6, and SRC were implicated in key pathways including MAPK signaling pathway, lipid and atherosclerosis, PI3K-Akt signaling pathway, and IL-17 signaling pathway." (PMID 39822742, 2024). "These pathways were mainly enriched in lipid and atherosclerosis, IL-17 signaling pathway, TNF signaling pathway, chemical carcinogenesis-receptor activation, AGE-RAGE signaling pathway in diabetic complications, and others." (PMID 38808131, 2024). "Studies related to the inflammatory storm in atherosclerosis also indicated overexpression of inflammatory cytokines IL-17, IL-1β, and TNF-α, along with elevated expression of Caspase-3, Caspase-9, and Caspase-12." (PMID 39494338, 2024). "In the progressive pathology of atherosclerosis, the inflammatory cytokine TNF-α has been demonstrated to play a critical role in the disruption of macrovascular and microvascular circulation, leading to endothelial cell destruction and dysfunction." (PMID 39080547, 2024). "Two studies found that TNF-α inhibitors led to more stable atherosclerosis metrics compared to methotrexate." (PMID 39739136, 2024). "This subgroup was also characterized by higher TNF-α levels, which have been shown to contribute to early atherosclerosis by increasing the subendothelial retention of LDL cholesterol in the vascular walls." (PMID 38542165, 2024). "This latter condition is associated with systemic inflammation and a surge in pro-inflammatory cytokines such as tumor necrosis factor-alpha (TNF-α) and interleukin-6 (IL-6), which are pivotal in atherosclerosis and CVD pathogenesis." (PMID 38540305, 2024). "Throughout the progression of atherosclerosis, TNF-α promotes the translocation of LDL to the subendothelial layer of blood vessel walls, leading to its accumulation and subsequent oxidation to oxidized LDL." (PMID 39796594, 2024). "According to the KEGG enrichment results, 48 KEGG pathways were enriched for the target genes, including the TNF signaling pathway, osteoclast differentiation, lipids, and atherosclerosis." (PMID 38457553, 2024).
atherosclerosis (continued). "Meanwhile, KEGG pathway enrichment analysis identified several significant biological pathways, including the IL-17 signaling pathway, TNF signaling pathway, and fluid shear stress and atherosclerosis pathways." (PMID 39697434, 2024). "For example, phosphorylation at S273 by cyclin-dependent kinase 5 (CDK5) has been shown to increase proinflammatory factors including TNF-α, IL-1β, and foam cell formation, which worsen atherosclerosis." (PMID 37833942, 2023). "Elegant lineage-tracing studies have recently demonstrated that endothelial-to-mesenchymal (endoMT) transitioning occurs during atherosclerosis, where inflammatory conditions (i.e., TNF + IFNy) were shown to further promote endoMT processes." (PMID 38034389, 2023). "TNF drives inflammation and plaque formation in atherosclerosis; therefore, TNF inhibitors can be used to prevent coronary atherosclerosis." (PMID 36742069, 2023). "It has been established that NOX4/ROS, which is primarily triggered by TNF-α, plays a significant role in the development of atherosclerosis." (PMID 38028719, 2023). "Down-regulated DEGs were involved in the KEGG pathway: TNF signaling pathway (hsa04668), fluid shear stress and atherosclerosis (hsa05418), NOD-like receptor signaling pathway (hsa04621), and cytokine–cytokine receptor interaction (hsa04060)." (PMID 37189834, 2023). "Upon binding to TNF-α, the receptor activates various intracellular signaling pathways (p38, p65, and JNK), which are involved in inflammatory responses associated with atherosclerosis." (PMID 37947623, 2023). "Overall, the unique genes are mainly involved in lipid and atherosclerosis, apoptosis, NF-κB signaling, TNF signaling, cancer pathways, and other signaling pathways related to CAC." (PMID 38203330, 2023). "The first three entries of enrichment were the AGE-RAGE signaling pathway in diabetic complications, lipid and atherosclerosis, and TNF signaling pathway." (PMID 36866869, 2023). "Conversely, B2 cells participate in adaptive immune responses and secrete cytokines IL-10 and TNF-α, which influence Treg development and potentially promote the formation of atherosclerosis." (PMID 38143759, 2023). "The intricate connection between atherosclerosis markers and pro-inflammatory cytokines, such as tumor necrosis factor-alpha (TNF-α) and interleukin-6 (IL-6), is a complex and highly significant area in cardiovascular research." (PMID 37893519, 2023). "The results showed that SELE, an adaptive immune gene, mainly regulates the TNF signalling pathway, cell adhesion molecules (CAMs) and fluid shear stress and atherosclerosis." (PMID 37849501, 2023). "Interleukins (IL-1β and IL-6), chemokines, interferon-γ (IFN-γ), and tumor necrosis factor-alpha (TNF-α) are the cytokines commonly associated with endothelial dysfunction, vascular inflammation, and atherosclerosis." (PMID 37629526, 2023). "The preincubation also prevented the downregulation of endothelial nitric oxide synthase (which contributes to atherosclerosis) induced by TNF-α." (PMID 37608809, 2023). "When stimulated with ox-LDL, in other inflammatory states, like atherosclerosis, macrophages responded with an increased expression of TNFα (tumor necrosis factor-alpha) and IL-6 (interleukin 6) genes." (PMID 37251403, 2023). "The relationship between CHI3L1 and atherosclerosis is closely related to macrophage activation, and the enhancement of TNF-α also promotes the expression of CHI3L1 in macrophages." (PMID 38003338, 2023). "In atherosclerosis, microRNA binding directly to human RNA-binding protein (HuR) regulates the formation of IL-6, TNF-α, IL-1β, and myocardial fibrosis via fibroblast activation and expansion." (PMID 38203612, 2023). "The second is the age−RAGE signaling pathway and TNF signaling pathway in lipid and atherosclerosis, diabetic complications, and the Toll-like receptor signaling pathway." (PMID 37747012, 2023).